KLF6 (KLF transcription factor 6)
Diseases named in the same sentence as KLF6 in open-access papers (continued):
Sharing a sentence is not in itself a finding about the gene and the disease.
tumor (continued). "An analysis of the correlation between UHRF1 expression and that of its target genes in scT‐LBLs demonstrated that the tumour suppressor genes FOXP1, PIK3R1 and KLF6 exhibited a significant negative correlation with UHRF1 expression." (PMID 40579780, 2025). "The KLF6, MYC, and FOSL2 genes did not seem to follow the EGR1/FOS expression pattern in the analyzed tumor samples." (PMID 39436655, 2024). "Statistical analysis showed that KLF6 expression is independent of age (p = 0.896), sex (p = 0.470), TNM stage (p = 0.611), tumor grade (p = 0.223), preoperative CA199 value (p = 0.525), and preoperative CEA value (p = 0.631)." (PMID 36615000, 2022). "Immunohistochemical results suggested that in tumor tissues, CASP8 and SAMSN1 showed high staining, TXNIP showed medium staining, while KLF6 and XCL1 showed negative staining; in normal tissues, KLF6 showed medium staining, CASP8 and SAMSN1 showed low staining, while TXNIP showed negative staining." (PMID 40149637, 2025). "Specifically, KLF6, BCL2, ETS1, and PLOD2 could provide insights into tumor biology, hypoxia adaptations, and aggressiveness without invasive biopsies." (PMID 40500522, 2025).
cancer (115 papers, 2008 to 2025). A tumor composed of atypical neoplastic, often pleomorphic cells that invade other tissues. "Through scRNA-Seq data, we detected high expression of SRY-box transcription factor 4 (Sox4) and Kruppel-like factor 6 (Klf6) in the C2 epithelial cell cluster, with Sox4 and Klf6 being associated with the maintenance of cancer stem cell stemness." (PMID 39774471, 2025). "A series of studies have shown that aberrant expression of KLF6 is implicated in the pathogenesis of a variety of diseases, such as cancer/inflammation-related diseases and cardiovascular diseases." (PMID 39215680, 2024). "There is considerable evidence that the inactivation of KLF6 by mutation or deletion is frequently observed in most human cancers." (PMID 33816511, 2021). "KLF6 is a relevant example; a range of functional and expression assays suggested that the dysregulation of KLF6 contributes to the onset of cancer, inflammation-associated diseases as well as cardiovascular diseases." (PMID 32998281, 2020). "The contradicting observations on the KLF6 mutational status and role in cancers have been further confounded by the discovery of KLF6 spliced variants and their involvement in regulating tumorigenesis, particularly KLF6-SV1." (PMID 32998281, 2020). "The hepatic growth factor and RAS signalling pathway have also been linked to enhancing the KLF6 alternative splicing event in cancer." (PMID 32998281, 2020). "In this review, we will specifically focus on the roles of KLF6 in driving cancer and inflammatory-associated disease pathogenesis." (PMID 32998281, 2020). "Our experimental analyses of the super enhancer upstream of KLF6 demonstrate the robustness of some cancer-associated super enhancers." (PMID 30858363, 2019). "Similar to our study on KLF4, it has been shown that splicing deregulation of KLF6 results in a specific variant, KLF6-v1, that is associated with an increased risk of various cancers and opposes KLF6(FL) effects." (PMID 27323810, 2016). "Mutations in cis-acting splicing elements were shown in both oncogenes (KIT, CDH17, and BRCA1/2) and tumor suppressors (LKB1 and KLF6), which have causal role in cancer initiation and progression." (PMID 28105922, 2016). "It was interesting to note that wtKLF6 was the dominant KLF6 variant in A549 lung epithelial cells both at basal level and in response to P. aeruginosa infection, in spite of them being a cancer cell line." (PMID 25010049, 2014). "KLF6-SV1, an oncogenic splice variant of the tumor suppressor KLF6 gene, is significantly up-regulated in several human cancers and its over-expression is associated with decreased survival in prostate and lung cancers." (PMID 24285959, 2013). "On the other hand, enforced expression of KLF6 variant 2 (SV2) induces cancer cell death by apoptosis." (PMID 24378751, 2013). "KLF6 inactivation has been implicated in a number of human cancers, including colorectal non-small cell lung gastric, astrocytic glioma, and nasopharyngeal." (PMID 24378751, 2013). "Examination of the published KLF6 mutations demonstrates that indeed a number of the cancer-defined mutations occur in the NLS and NES domains." (PMID 20844588, 2010). "KLF6 was implicated in cancer, inflammatory diseases, and cardiovascular disorders." (PMID 40936936, 2025). "While Krüppel-like factor 6 (KLF6) dysregulation has been implicated in cancer and cardiovascular diseases, its role in IA remains unclear." (PMID 39215680, 2024). "KLF6 is a tumor suppressor gene associated with several types of cancer." (PMID 37886042, 2023). "It has been pointed out that PCR amplification artefacts due to the use of archived cancer tissues or other technical issues might contribute to these discrepancies in the KLF6 mutational status." (PMID 32998281, 2020). "Nonetheless, the KLF6 mutational status in cancer has been a subject of debate." (PMID 32998281, 2020).
cancer (continued). "In further agreement with our hypothesis that regulation of nucleo-cytoplasmic transport is a critical determinant of KLF6 function, we demonstrated that mutations in the KLF6 NLS domain result in decreased transcriptional activation of two cancer-relevant targets, p21 and E-cadherin." (PMID 20844588, 2010). "Cancer cell-derived exosomes containing miR-200b induce M2 macrophage polarization via KLF6 (Kruppel-like factor 6) reduction." (PMID 40136652, 2025). "The isoforms act as antagonists of the functional KLF6 isoform, cancers tend to be aggressive and metastasis." (PMID 40190563, 2025). "Apart from its correlation with cancer development, KLF6 has been demonstrated to have a role in several processes, including inflammation, cell proliferation and apoptosis, and body growth and development." (PMID 40506042, 2025). "We found that FOSL2 collaborates with KLF6 to regulate the expression of SEMA3C, a protein that has been implicated in cancer progression." (PMID 40082673, 2025). "Other notable examples of ACR-to-gene links include TF genes KLF6 and PPARG, linked respectively to one and two enhancers that gain accessibility in PDAC cancer cells." (PMID 37914932, 2023). "Expression of KLF2 and KLF6 has previously been shown to increase in cancer cells following treatment with the lipophilic statin lovastatin and an association between induction of these genes and apoptosis has been demonstrated." (PMID 36803614, 2023). "KLF6 also inhibits cancer cell proliferation through p21-mediated cyclin D1/CDK4 expression, but this pathway is regulated by miR-181a." (PMID 36761967, 2023). "PITRM1-AS1 has recently been shown to interact with KLF6, a transcription factor and tumor suppressor that is dysregulated in several cancers." (PMID 37444464, 2023). "Genetic alterations and the aberrant expression of KLF6 are correlated with the formation and progression of cancer." (PMID 36615000, 2022). "Owing to the different expression of KLF6 between pancreatic normal cells and cancer cells, we further explored the potential function of KLF6 in PAAD." (PMID 36615000, 2022). "In contrast to these studies, several groups proposed that genetic alterations of KLF6 were infrequently observed and overexpressed in some types of cancer." (PMID 36615000, 2022). "Playing a central role in modulating these processes, the human KLF6 gene has been reported to influence tumorigenesis and the development of cancer." (PMID 36615000, 2022). "Presently, scholars have proved the important role of KLF6 in the tumorigenesis of certain cancers through a large number of experiments." (PMID 36615000, 2022). "Based on the TCGA PanCancer Atlas database of the cBioPortal website, we obtained the relationship between KLF6 and the incidence of various cancers." (PMID 34776953, 2021). "Among the three KLF6 splice variants, KLF6-SV1 is the most explicit in oncogenesis, and it can obviously antagonize the anti-cancer function of KLF6." (PMID 33816511, 2021). "The roles of KLF6 in cancer—particularly, the full-length KLF6—has been the subject of active investigations and discussions." (PMID 32998281, 2020). "Analysis of the publicly available large-scale The Cancer Genome Atlas (TCGA) RNA-Seq data showed that the expression of the KLF6 gene varied among cancer types." (PMID 32998281, 2020). "Among the analysed cancer types, bladder cancer had the highest frequency of KLF6 genetic alterations—36 out of 411 cases—of which 2.19% were mutations, 6.33% were amplifications and 0.24% were deep deletions." (PMID 32998281, 2020).
cancer (continued). "Inactivation of KLF6 has been frequently found in most human cancers, including lung, hepatocellular, colorectal, prostate, gastric, nasopharyngeal, astrocytic glioma, and ovarian cancer." (PMID 32733026, 2020). "Apart from these, the expression of KLF6 was found to be downregulated in other cancer types as compared to their respective normal tissues." (PMID 32998281, 2020). "Since KLF6 plays a central role in modulating these processes, genetic alterations and/or the aberrant expression of KLF6 have been reported to support the formation and progression of many cancer types." (PMID 32998281, 2020). "This is due to the contradicting reports on the full-length KLF6 roles and mutations status in a myriad of studies, as well as variations in the KLF6 gene expression level in different cancer types." (PMID 32998281, 2020). "Nonetheless, shreds of evidence from functional studies have demonstrated that full-length KLF6 possesses growth-suppressive roles in several cancers, such as prostate, ovarian, colorectal and liver." (PMID 32998281, 2020). "Large-scale cancer genome re-sequencing efforts suggest that KLF6 is rarely inactivated via genetic alterations." (PMID 30858363, 2019). "Several splice variants that are known to be involved in cancer have been identified in PCa, including VEGFA, KLF6, BCL2L2, ERG, FGFR2, TMPRSS2-ERG and AR 3,4." (PMID 31632503, 2019). "In this review, aberrant splicing events in cancer-associated genes, namely BCL2L1, FAS, HRAS, CD44, Cyclin D1, CASP2, TMPRSS2-ERG, FGFR2, VEGF, AR and KLF6, will be discussed." (PMID 30463359, 2018). "Another TSG, KLF6, is frequently inactivated by loss of heterozygozity (LOH), somatic mutation, and/or decreased expression in human cancer." (PMID 28146424, 2017). "KLF6 is down-regulated in several types of cancers, and overexpression of wild-type KLF6 inhibits HCC cells proliferation and migration, while KLF6 down-regulation by siRNA increases HepG2 proliferation." (PMID 28572744, 2017). "Accumulating evidence suggests that the tumor suppressor gene Krüppel-like factor 6 (KLF6) plays important roles in both development and progression of cancer." (PMID 27057625, 2016). "Krüppel-like factor 6 (KLF6) is a tumor suppressor gene that is functionally inactivated through a range of mechanisms in several types of cancer, including HCC." (PMID 27057625, 2016). "Krüppel-like transcription factor 6 (KLF6) is a novel tumor suppressor gene and is involved in the pathogenesis of many cancers." (PMID 27690088, 2016). "In contrast to the tumour suppressive action of wtKLF6, the splice variants of KLF6, particularly SV1, have been found to have oncogenic properties and have been implicated in several types of cancer including lung, liver, ovarian and prostate." (PMID 25010049, 2014). "KLF6 is frequently inactivated in human cancer and has significant roles in cellular proliferation, apoptosis and differentiation." (PMID 23977008, 2013). "KLF6 inactivation and KLF6-SV1 overexpression have been associated not only with the progression of several human cancers but more importantly with patient survival." (PMID 22419853, 2012). "Nevertheless, several other large studies established that genetic alterations of KLF6 are rarely found in distinct types of human cancers." (PMID 21799854, 2011). "Given the cancer-relevant and antagonistic functions of KLF6 and KLF6-SV1 it will be important to define the functionality of the putative NLS, the 5BR, as well as the role of nucleo-cytoplasmic shuttling in regulating KLF6/KLF6-SV1 function." (PMID 20844588, 2010).
cancer (continued). "Nevertheless, a number of other studies established that genetic alterations of KLF6 were infrequently observed in distinct types of human cancers or, in addition the klf6 gene expression was enhanced in some tumors." (PMID 20126619, 2010). "Specifically, the elucidated interplay between KLF6, TAF6L and FOSL2, along with their regulatory influences on SEMA3C and the Wnt-β-catenin pathway, enhancing our understanding of the complex networks underlying cancer drug resistance." (PMID 40082673, 2025). "The KLF family of transcription factors, including both KLF4 and KLF6, have a well‐established role in cancer progression, and we showed direct regulation of CFTR by KLF5 in airway epithelial cells where this factor has a critical role in wound repair and innate immunity." (PMID 40785146, 2025). "Finally, pan-cancer analysis emphasized the biological significance of KLF6 in multiple types of tumors and its clinical utility in assessing cancer prognosis." (PMID 38773440, 2024). "Furthermore, we explored the biological and clinical relevance of KLF6 across different cancer types." (PMID 38773440, 2024). "In addition, KLF6 was closely related to overall survival, disease-free survival, disease-specific survival, and progression-free survival in pan-cancer." (PMID 38773440, 2024). "Moreover, miR-653 served as carcinoma-promoting gene via targeting KLF6, and circSETD3 knockdown significantly reversed the inhibitory effect of KLF6 overexpression on CRC cells." (PMID 36605481, 2023). "Moreover, analyses of the more recent TCGA genomic data revealed that KLF6 was rarely deleted/inactivated in the previously studied cancers." (PMID 32998281, 2020). "In addition, KLF6 also suppresses cancer cell metastasis via repressing the transcription of E2F116 or MMP917." (PMID 32733026, 2020). "This could potentially be achieved by targeting the specific upstream regulators that mediate the full-length KLF6 repression or inactivation in cancers such as the miRNAs and long noncoding RNAs." (PMID 32998281, 2020). "On the other hand, direct KLF6 targeting might be more relevant and applicable to the cancer types where KLF6 functions as pro-oncogene." (PMID 32998281, 2020). "Collectively, the percentage of cancer cases that had the KLF6 gene alteration were quite low." (PMID 32998281, 2020). "Based on our results, we hypothesized that KLF6 directly mediated miR‐191‐regulated cancer cell proliferation." (PMID 31334580, 2019). "KLF6 plays a key role in the development and progression of multiple human cancers." (PMID 29854578, 2018). "Although KLF6 alternative splicing is present in both normal and cancerous tissues, it was suggested that the ratio between wild-type and alternatively spliced forms have effects on many key processes regulating cancer cell growth and metastasis." (PMID 29854578, 2018). "In addition to gastric cancer, functional inactivation of KLF6 was observed in a number of other human cancers including prostate, colorectal, ovarian, liver, and breast cancer." (PMID 27690088, 2016). "We previously demonstrated that KLF6 is profoundly down regulated during liver carcinogenesis and may protect cancer cells from apoptosis." (PMID 24378751, 2013). "We are currently exploring whether miR-181a and miR-122 regulate KLF6 expression in liver-derived cancer cells." (PMID 24378751, 2013). "We and other have demonstrated that KLF6 is also downregulated during liver carcinogenesis and this downregulation may protect cancer cells from apoptosis." (PMID 24378751, 2013). "The KLF6 protein itself was degraded when cancer cells underwent apoptosis." (PMID 24324791, 2013). "KLF6 is frequently inactivated in a number of human cancers." (PMID 20844588, 2010). "In addition, in 12 HCC patients who underwent surgery, the serum levels of LCAC-16:0 were significantly correlated with relative protein expression of KLF6 in the cancer tissues, providing further support for the conclusion that LCACs activate the KLF6 in vivo." (PMID 40370557, 2025).